MMP12 (matrix metallopeptidase 12)
Description:
May be involved in tissue injury and remodeling. Has significant elastolytic activity. Can accept large and small amino acids at the P1' site, but has a preference for leucine. Aromatic or hydrophobic residues are preferred at the P1 site, with small hydrophobic residues (preferably alanine) occupying P3.
Synonyms: MME; ME; hME; MMP-12
Tractability: Small molecule: a drug acting on it is in phase 2 or 3 trials; a structure with a bound ligand is known; a high-quality ligand is known; it has a high-quality binding pocket. Antibody: UniProt places it where antibodies can reach, with high confidence; its Gene Ontology location is reachable by antibodies, with high confidence; UniProt predicts a signal peptide or a membrane-spanning region. PROTAC: a small molecule that binds it is known.
Target class: Metallo protease; Metallo protease M10A subfamily; Metallo protease MAM clan; Protease; Enzyme
Chemical probes: BAY-7598 (high quality)
Gene: Protein-coding gene on chromosome 11 (102,862,736 to 102,874,982, reverse strand). Ensembl gene ENSG00000262406.
Subcellular location: Secreted, extracellular space, extracellular matrix
Pathways (Reactome):
Extracellular matrix organization: Collagen degradation; Degradation of the extracellular matrix
Gene Ontology:
Molecular function: calcium ion binding; collagen binding; core promoter sequence-specific DNA binding; metalloendopeptidase activity; sequence-specific DNA binding; zinc ion binding; endopeptidase activity; serine-type endopeptidase activity; metallopeptidase activity; peptidase activity
Biological process: elastin catabolic process; negative regulation of endothelial cell-matrix adhesion; positive regulation of epithelial cell proliferation involved in wound healing; positive regulation of transcription by RNA polymerase II; protein import into nucleus; proteolysis; wound healing, spreading of epidermal cells; collagen catabolic process; extracellular matrix disassembly; extracellular matrix organization; response to amyloid-beta; cellular response to virus; negative regulation of transcription by RNA polymerase II; negative regulation of type I interferon-mediated signaling pathway; positive regulation of gene expression; positive regulation of interferon-alpha production; positive regulation of type I interferon-mediated signaling pathway; regulation of defense response to virus by host
Cellular component: cytoplasm; extracellular region; nucleus; extracellular matrix
Genetic constraint (gnomAD): Loss-of-function variants: 43 observed, 36.59 expected, observed/expected ratio (o/e) 1.18, 90% interval 0.92 to 1.51. The upper end of that interval is the gene's LOEUF score, 1.51, which puts it in group 6 of 6, group 1 being the genes least tolerant of losing a copy. Missense variants: 455 observed, 499.43 expected, observed/expected ratio (o/e) 0.91, 90% interval 0.84 to 0.98. Synonymous variants: 177 observed, 167.37 expected, observed/expected ratio (o/e) 1.06, 90% interval 0.94 to 1.2.
Homologues: Orthologues: chimpanzee MMP12 (99% identical), macaque MMP12 (91% identical), rabbit MMP12 (73% identical), dog MMP12 (70% identical), pig MMP12 (69% identical), guinea pig MMP12 (66% identical), mouse Mmp12 (62% identical), rat Mmp12 (59% identical), tropical clawed frog mmp8 (46% identical), zebrafish mmp13b (44% identical), zebrafish mmp30 (40% identical), zebrafish mmp25b (33% identical), and 11 more. Paralogues in human: MMP3 (51% identical), MMP10 (50% identical), MMP1 (48% identical), MMP27 (47% identical), MMP8 (46% identical), MMP13 (46% identical), MMP20 (43% identical), MMP2 (41% identical), MMP24 (40% identical), MMP14 (39% identical), MMP15 (39% identical), MMP16 (38% identical), and 11 more.
Diseases named in the same sentence as MMP12 in open-access papers:
MMP12 is named in the same sentence as 290 diseases in open-access papers, as found by Europe PMC text mining. Sharing a sentence is not in itself a finding about the gene and the disease. The quoted sentences say what the papers report.
emphysema (178 papers, 2004 to 2025). "Previous studies had demonstrated that elevated levels of MMP-12 in the sputum were associated with emphysema severity in COPD and asthma patients." (PMID 39011515, 2024). "Many studies reported the overexpression and increased activity on MMP12 linked to the development of emphysema and COPD." (PMID 38771844, 2024). "Mechanistically, our RNAseq and qPCR analysis revealed emphysema in CS exposed mice was accompanied with an upregulation of COPD susceptible gene Mmp-12, a well-recognised genetic factor for COPD both in humans and in pre-clinical models." (PMID 38614991, 2024). "MMP-12 is a negative regulator of glucose metabolism and is also implicated in the development of emphysema." (PMID 37819895, 2023). "They suggested that basophil-derived IL-4 promoted the differentiation of infiltrating monocytes into MMP-12–producing IMs that caused the alveolar wall destruction and emphysema formation." (PMID 37205111, 2023). "Our previous studies showed that chronic airway inflammation in βENaC-Tg mice is associated with emphysema-like structural damage of distal airspaces and that NE and MMP-12 are implicated in this process." (PMID 36362203, 2022). "Increased MMP-12 activity from inflammatory macrophages is also associated with abdominal aortic aneurysms, atherosclerosis, and emphysema." (PMID 35456498, 2022). "MMP-12 levels were also higher in Cluster 1 than in Cluster 2 and they were associated with greater prevalence of emphysema." (PMID 36480517, 2022). "Increased endothelial monocyte-activating protein-II (EMAPII), MMP-9, and MMP-12 levels are the primary cause of the development of emphysema by Moraxella." (PMID 35740358, 2022). "Nippostrongylus brasilensis infection has been reported to cause emphysema with the progression of enlarged airspace overtime and increased expression of Mmp12." (PMID 35264261, 2022). "Mmp12 has been associated with pathological conditions and is reported to be a major contributing factor to the development of emphysema." (PMID 35264261, 2022). "In particular, high extracellular matrix MMP-12 levels are strongly associated with an emphysema/COPD phenotype." (PMID 35053420, 2022). "AHR is mediated mostly by increased IFN-γ and RANTES concentrations, while the risk of emphysema was related to the activation of the IL-17 → MCP-1 → MMP-9 → MMP-12 axis." (PMID 36293561, 2022). "These clinical results are supported by experimental data demonstrating (A) that elastase causes lung tissue destruction and (B) that mice deficient in Mmp12 are resistant to CS-induced emphysema." (PMID 34912233, 2021). "The pathogenesis is attributable to emphysema caused by the decomposition of elastin, which constitutes the alveoli, by MMP-12." (PMID 34703996, 2021). "Alveolar macrophages produce Mmp12, which is critical for lung structural remodeling in CS-associated lung diseases, including emphysema, asthma, and lung cancer." (PMID 34912233, 2021). "MMP-12 is a protease associated with emphysema that is elevated in the sputum and BAL of COPD patients." (PMID 34425800, 2021). "We show for the first time that the loss of IL10 increases expression of MMP12, an elastase known to contribute to clinical emphysema." (PMID 32170906, 2020). "We demonstrate that the systemic loss of the IL10 enhances MMP12 expression in the lung and reduces the macrophage prosurvival effects on alveolar epithelial cells, both of which contribute to the emphysema phenotype." (PMID 32170906, 2020). "It seems to be necessary for emphysema development, and specifically, it was shown that elevated levels of MMP-12 in the sputum are associated with emphysema severity in COPD." (PMID 30658596, 2019). "For example MMP-12, macrophage elastase, is responsible for the breakdown of elastin and it is associated with a number of inflammatory pathologies such as aortic aneurysm, emphysema, and rheumatoid arthritis." (PMID 31572676, 2019).
emphysema (continued). "MMP-1, which degrades collagen, and MMP-12, which degrades elastin, have both been strongly implicated in the development of smoke-induced emphysema, at least in animal models." (PMID 30789935, 2019). "A pathogenic role of MMP-12 has also been demonstrated in COPD whereby emphysema caused by CS was abolished in MMP-12−/− mice." (PMID 31636311, 2019). "MMP-12, macrophage elastase, is also involved in extracellular matrix degredation and is associated with the development of emphysema and the increase in intestinal tight junction permeability in IBD." (PMID 29483875, 2018). "Study also implicated that rs652438 SNP changes the MMP-12 activity and increased macrophage infiltration and emphysema in the lungs of COPD patients." (PMID 28848433, 2017). "Ig-Hepta−/− mice spontaneously developed a pulmonary emphysema-like symptom characterized by a reduced number and an increased volume of alveoli, which was associated with a marked increase of matrix metalloproteinase 12 (Mmp12)." (PMID 23922714, 2013). "Increased activity of MMP-12 from inflammatory macrophages is associated with abdominal aortic aneurysm, atherosclerosis, and emphysema." (PMID 23642232, 2013). "In contrast to a prior study, higher MMP-12 levels were associated with lower emphysema scores on CT." (PMID 23441181, 2013). "RNA sequencing analysis of human bronchial epithelium shows that IL-17 and IL-22 can induce MMP3 and MMP12, the latter gene implicated in cigarette smoke-induced emphysema." (PMID 21647421, 2011). "Mice over-expressing MMP1 develop emphysema, whilst those deficient in MMP12 are relatively protected." (PMID 17054776, 2006). "Second, the principal Th1 chemokines, MIG and IP-10, are linked to a pro-elastolytic lung environment because these cytokines upregulate the elastase MMP12, which is associated with emphysema." (PMID 15526056, 2004). "Epithelial restricted integrin α vβ 6-null mice develop age-related emphysema through the loss of activation of latent TGF-beta which leads to an increase in macrophage MMP-12 expression." (PMID 15522115, 2004). "Notably, MMP-12-deficient mice exposed to cigarette smoke are resistant to emphysema development and show reduced macrophage infiltration, underscoring MMP-12′s central role in disease progression." (PMID 40940719, 2025). "It was further shown that the pre-existing type 2 immune signature upon the commencement of CS exposure likely contributed to the onset of emphysema with increased production of MMP-12 and recruited pathogenic lung macrophage populations such as interstitial macrophages." (PMID 38614991, 2024). "Similarly, MMP12-deficient mice exhibited the suppression of the pulmonary influx of macrophages and attenuation of emphysema development after prolonged exposure to CS." (PMID 38891820, 2024). "Excess MMP12 has been associated with lung injury and emphysema in mice." (PMID 37078230, 2023). "Thus, loss of TRPML3 was discovered to exacerbate emphysema formation and cigarette smoke induced COPD due to dysregulated matrix metalloproteinase 12 (MMP-12) levels in the extracellular matrix of the lung, a known risk factor for emphysema/COPD." (PMID 35053420, 2022). "However, in both pulmonary compartments, animals with cholinergic deficiency and emphysema (VAChT KDHOM-PPE) showed more augment of MMP-12 expression than observed in wild-type (WT-PPE) (P < 0.05)." (PMID 34354132, 2021). "More research is needed to validate whether hypomethylated Mmp12 could serve as a potential biomarker for increased susceptibility to adult emphysema, asthma, and lung cancer following in utero SHS exposures." (PMID 34912233, 2021). "In light of this finding, Atp8b1 mutant mice may be susceptible to develop age-induced emphysema as a result of increased MMP12 levels." (PMID 27689529, 2016).
emphysema (continued). "We demonstrated that B cells organized into iBALT structures were involved in inducing and maintaining a severe inflammatory response after CS exposure, causing subsequent emphysema development by regulation of macrophage accumulation and macrophage-derived MMP12 production." (PMID 26284585, 2016). "Abnormal regulation of MMP-12 expression has been implicated in abdominal aortic aneurysm, atherosclerosis, and emphysema, but the underlying mechanisms remain unclear." (PMID 26822129, 2016). "Furthermore, early signs of emphysema were only observed in CS-exposed vitamin D deficient mice, which was accompanied by elevated levels of MMP-12 in the lung." (PMID 26376849, 2015). "These early signs of emphysema may be (partially) explained by the increased expression of MMP-12 in vitamin D deficient mice following CS exposure." (PMID 26376849, 2015). "Furthermore, sputum MMP-12 concentrations correlate with the extent of emphysema as determined by CT and polymorphisms in the MMP-12 promoter have been associated with changes in lung function." (PMID 23441181, 2013). "Of note mmp12 has been associated with the emphysema subtype of COPD." (PMID 23675439, 2013). "Furthermore, several polymorphisms in MMP1, MMP9, and MMP12 genes have been associated to emphysema and related phenotypes." (PMID 23734748, 2013). "Studies have shown that the development of emphysema in β6 deficient mice correlates tightly with the upregulation of MMP12, suggesting that MMP12 could serve as a surrogate biomarker to assess for this particular consequence." (PMID 22013449, 2011). "According to animal studies, MMP-12 deficiency protects against cigarette smoke induced emphysema." (PMID 18001475, 2007). "Indeed, MMP-12 has been reported to be essential in tissue remodelling associated with emphysema in mice exposed to cigarette smoke." (PMID 16504062, 2006). "In addition, products of activated leukocytes including MMP-12 and NE can cause destruction of elastin fibres and other components of the interalveolar septum adjacent to these small airways, leading to centrilobular emphysema." (PMID 27046438, 2016). "In addition, mice deficient in MMP12 (mainly produced by macrophages) were completely protected from cigarette-smoke-induced emphysema even though they could still produce neutrophil elastase." (PMID 23533311, 2013). "MMP12 deficiency has been shown to protect mice against emphysema after chronic exposure to cigarette smoke, implying that MMP12 may be the key proteinase in the development of emphysema in this species." (PMID 15526056, 2004). "MMP12 is a macrophage metalloprotease responsible for the proteolytic attack on the alveolar wall matrix, resulting in emphysema." (PMID 40496925, 2025). "In recent experimental models, basophils have been identified as having a role in emphysema development through IL-4-mediated generation of MMP-12-producing macrophages." (PMID 38622557, 2024). "IL-13 is capable of promoting M2 polarisation and MMP-12 production in macrophages and in mice, where over-expression of IL-13 was found to induce emphysema that was dependent on MMPs, with eosinophils identified to be a rich source of IL-13." (PMID 38614991, 2024). "Matrix metalloproteinase-12 (MMP-12) played a key role in developing elastase-induced emphysema and was mainly expressed by IMs." (PMID 37205111, 2023). "Macrophages contribute to CS-induced emphysema development in mice, in part, by releasing Mmp-12 (which degrades lung elastin) and oxidants." (PMID 36787195, 2023). "MMP12, a member of the MMPs family, mediates alveolar destruction during emphysema and it promotes the pathogenesis of chronic bronchitis." (PMID 36996500, 2023). "The authors concluded that the basophil-derived IL-4/monocyte–derived IM/MMP-12 axis plays a role in emphysema development." (PMID 37205111, 2023). "Studies have indicated that MMP-12 interacts with the enzyme macrophage elastase in smokers, resulting in emphysema in COPD patients." (PMID 36830984, 2023).
emphysema (continued). "The SAEs were attributed to increased alveolar inflammation, increased MMP12 generation, and emphysema due to the long half-life of BG0001132,33." (PMID 37704610, 2023). "In animal studies, MMP-12 was essential for emphysema formation in a CS-induced mouse model and for macrophage chemotactic activity in smoke-exposed lungs." (PMID 37592330, 2023). "Unsurprisingly, expression of elastin degrading MMP-12 was inversely correlated with the carbon monoxide diffusing capacity of the lung and alveolar volume in patients with emphysema." (PMID 37001705, 2023). "This family of enzymes is recognized as a key factor in lung ECM turnover and the members of the family, including MMP-9 and MMP-12, seem to be involved in an imbalance in protease and antiprotease activity, leading to the development of emphysema." (PMID 36767357, 2023). "For instance, there is strong evidence of the development of emphysema after smoking exposure which depends on MMP-12/Macrophage elastase." (PMID 36569308, 2022). "A recent study showed that, in alveolar macrophages, CS promotes M2 polarisation and the increase in IL4 inducing MMP12 release, which is involved in emphysema." (PMID 35740358, 2022). "A higher IL-17 expression correlates with higher MMP-12 mRNA expression, which plays a significant role in the formation of emphysema; a stimulation of the IL-17 → MCP-1(Ccl-2) → MMP-9 → MMP-12 axis is crucial." (PMID 36293561, 2022). "Chronic lung inflammation induced by IL-13 promotes emphysema via the stimulation of alveolar macrophages to release matrix metalloproteinase (MMP)-12 and induces airway space enlargement." (PMID 35740358, 2022). "We show here a link between an endolysosomal cation channel, TRPML3, and the development of lung dysfunction and an emphysema-like phenotype in Trpml3−/− mice due to the inability of Trpml3−/− AMΦ to appropriately regulate MMP-12 levels in BALF." (PMID 35031603, 2022). "While the role of MMP-12 in emphysema and COPD pathology is well established, it remains largely unclear what the molecular components are which regulate the secretion of MMP-12 and how clearance of excessive MMP-12 levels in the ECM/BALF is regulated." (PMID 35031603, 2022). "Our observations, together with previous findings, suggest that F. nucleatum has the potential to increase the progression of emphysema by inducing the release of MMP12 and perforin in patients with COPD." (PMID 35034433, 2022). "HP dams also had increased expression of Mmp12 (P = 0.0480), an elastin degrading enzyme which plays a role in pulmonary emphysema development, compared to LP dams." (PMID 35264261, 2022). "Evidence for a relevant role in emphysema/COPD development is less established for MMP-8 compared to MMP-12, in particular in the mouse model." (PMID 35031603, 2022). "It is widely acknowledged that MMP12 is essential for the development of emphysema in mice exposed to CS due to its massive capacity to degrade extracellular matrix." (PMID 33828547, 2021). "Second, IFN-γ induces the release of matrix metalloproteinase-12 (MMP-12) in a transgenic mouse model, leading to inflammation and emphysema." (PMID 34375314, 2021). "It has been recently reported that IM is a major producer of MMP-12 in the lungs in a mouse emphysema model." (PMID 34425800, 2021). "Overexpression of MMP12, involved in airway remodeling, leads to the destruction of alveolar walls during emphysema development." (PMID 34912233, 2021). "We then isolated IMs from digested lungs of the emphysema model and examined the levels of MMP-12 mRNA." (PMID 34425800, 2021). "IL-4 secreted by activated basophil would induce a shift from lung-infiltrating monocyte to interstitial macrophage and IL-4/macrophage/macrophage-derived MMP-12 axis plays an important role in the development of emphysema." (PMID 34259107, 2021). "It has been suggested that eosinophil-derived IL-13 enhances emphysema by stimulating macrophages to secrete MMP-12." (PMID 34950055, 2021).